PIK3CA (phosphatidylinositol-4,5-bisphosphate 3-kinase catalytic subunit alpha)
Diseases named in the same sentence as PIK3CA in open-access papers (continued):
Sharing a sentence is not in itself a finding about the gene and the disease.
colorectal cancer (continued). "For instance, 5-fluorouracil (5-FU) has been noted to augment the antitumor activity of CB-839 in PIK3CA mutant colorectal cancers, and the proteasome inhibitor carfilzomib has shown synergistic effects when used with CB-839 in multiple myeloma." (PMID 39695080, 2024). "These mutations are frequently seen in colorectal cancer, whereas KRAS, PIK3CA, and APC mutations are rarely observed in prostate cancer." (PMID 39902031, 2024). "PIK3CA, which encodes the p110α catalytic subunit of PI3 kinase, is frequently mutated in human cancers, including 30% of colorectal cancers (CRCs)." (PMID 38194275, 2024). "Mutations in the PIK3CA and KRAS genes are commonly found in colorectal cancer and are associated with increased tumor risk." (PMID 38898987, 2024). "Here, we report that a combination of glutaminase inhibitor CB-839 and 5-FU inhibited the growth of PIK3CA-mutant colorectal cancers (CRCs) in xenograft, syngeneic, and genetically engineered mouse models in part through NETs." (PMID 38194275, 2024). "In this issue of the JCI, Li and colleagues focused on the impact of chemotherapy on colorectal cancer (CRC), specifically those cases with PIK3CA mutations, which account for 30% of CRC cases." (PMID 38426501, 2024). "The PIK3CA gene has been shown to be oncogenic and involved in the pathophysiology of cervical, breast, and colorectal cancer." (PMID 38674026, 2024). "PIK3CA/p110α phosphorylation at Y317 and Y508 play important role in tumorigenesis of colorectal cancer through two independent pathways." (PMID 37689735, 2023). "evaluate deep-learning-based prediction for MSI, BRAF, KRAS, NRAS, and PIK3CA biomarker status in colorectal cancer from histopathology slides." (PMID 36958327, 2023). "We conducted these experiments using HCT116 cells, a well-established model of colorectal cancer encoding the oncogenic KRAS G13D and PIK3CA H1047R proteins." (PMID 37811895, 2023). "In the DFCI cohort, colorectal cancers with wild type BRAF had TMB above 200 in 35% of cases when PIK3CA was mutant and in 18.5% of cases when PIK3CA was also wild type." (PMID 36079062, 2022). "The antitumor effects of antiplatelet agents have been broadly investigated in colorectal cancer with positive results, especially in subgroups with the expression of COX-2 and mutated PIK3CA genes." (PMID 36358749, 2022). "Post-diagnosis regular aspirin use was associated with reduced colorectal cancer-specific and overall mortality, especially in patients with positive PTGS2 (COX-2) expression and mutated PIK3CA tumors, reported by a meta-analysis." (PMID 36545311, 2022). "Colorectal SRCC is a rare subtype of colorectal cancer with distinctive molecular characteristics, including a low incidence of KRAS, PIK3CA, and APC mutations." (PMID 34997025, 2022).
colorectal cancer (continued). "The two V600E BRAF mutant/PIK3CA wild type colorectal cancer cell lines, LS411N and CL34, that are MSI high have consistently a high mutation count." (PMID 36295658, 2022). "Colorectal cancer cell line models recapitulate the presence of BRAF and PIK3CA mutations as encountered in clinical colorectal cancer samples, and also duplicate the frequent presence of MSI in these cases." (PMID 36295658, 2022). "In total, 22 of 534 profiled colorectal cancer patients in the TCGA cohort (4.1%) had mutations in both BRAF and PIK3CA oncogenes." (PMID 36079062, 2022). "Regarding the prevalence of mutations in other commonly mutated oncogenes and tumor suppressors, there are significant differences between colorectal cancers depending on the presence of BRAF and PIK3CA mutations." (PMID 36079062, 2022). "Our study is the first to show an association between the seventh PIK3CA variant (c.3157A>G, exon 21) detected in our CRC patients and colorectal cancer." (PMID 35723313, 2022). "PIK3CA mutation and PTEN suppression lead to tumorigenesis and drug resistance in colorectal cancer (CRC)." (PMID 35619132, 2022). "It is also mutated in 33.9% of colorectal cancers with BRAF mutations and in 19% of cancers with PIK3CA mutations." (PMID 36295658, 2022). "By inhibiting AKT/mTOR signaling, aspirin also promoted RSL3-induced ferroptosis in PIK3CA-mutant colorectal cancer cells." (PMID 36545311, 2022). "To this end, we have previously obtained a stable complex comprised of the internalizing anti-EGFR-antibody cetuximab bound to cationic protamine and the anionic siRNA against KRAS and PIK3CA that specifically enters colorectal cancer cells." (PMID 36457063, 2022). "In contrast, in the TCGA cohort, colorectal cancers with wild type BRAF had TMB above 200 in 16.8% of cases when PIK3CA was mutant and in 7.3% of cases when PIK3CA was wild type." (PMID 36079062, 2022). "BRAF mutant patients and even more so BRAF/PIK3CA double mutant colorectal cancers in TCGA tended to be of earlier stage (stages I and II) than BRAF wild type disease (p = 0.003)." (PMID 36079062, 2022). "These cell lines and the cell line NCI-H508 also possess deletions of PRKN, encoding for ubiquitin ligase parkin, which is the only recurrent deletions in BRAF/PIK3CA double mutant colorectal cancer cell lines." (PMID 36295658, 2022). "In summary, the results of this work suggest that patients with a combination of wild-type PIK3CA and mutated-KRAS tumors in particular benefit from aspirin use after diagnosis of colorectal cancer." (PMID 34638442, 2021). "The results of this study conclusively underline that the roles of the PIK3CA and KRAS mutational status as potential predictive markers for adjuvant therapy with aspirin in patients with colorectal cancer require prospective studies." (PMID 34638442, 2021). "Our study demonstrated the known driver mutations seen in colorectal cancer such as APC, KRAS, BRAF and PIK3CA, but also more novel mutations that would potentially be targetable by molecular agents." (PMID 33632293, 2021). "PIK3CA, the catalytic subunit of PI3K, undergoes mutation in many different tumors, including colorectal cancer." (PMID 33237662, 2021).
colorectal cancer (continued). "There were 4, 30, 21, and 3 mutation types in PIK3CA that were classified as Tier I, II, III, and IV variants in colorectal cancer, respectively." (PMID 33842311, 2021). "In colorectal cancer (CRC), mutations in the PIK3CA gene, which encodes for the p100α subunit of PI3K, lead to upregulation of GPT2 and reliance on glutamine-derived TCA intermediates to sustain growth." (PMID 33669382, 2021). "Previous studies had reported a close relationship between PIK3CA and immune cells or immune response in cancers, including lung and colorectal cancer." (PMID 34367282, 2021). "For example, RET is altered in 2.94% of colorectal carcinoma patients and, further, PI3K signaling can be activated by direct mutation or amplification of PIK3CA or loss of PTEN." (PMID 34885128, 2021). "In this experiment, we investigated the difference in PI3K (p110α) protein expression between PIK3CA mutant and PIK3CA wild-type colorectal cancer." (PMID 32000660, 2020). "Aspirin, as a non-steroidal anti-inflammatory drug, can improve the survival rate of patients with colorectal cancer, while aspirin is effective in patients with PIK3CA mutant colorectal cancer (CRC)." (PMID 32000660, 2020). "Some previous studies have shown that PIK3CA mutant colorectal cancer is resistant to some chemotherapy drugs." (PMID 32000660, 2020). "It was found that the expression of Raptor in the cancer tissue with PIK3CA mutant was higher than the expression of the wild-type PIK3CA colorectal cancer tissue." (PMID 32000660, 2020). "Two different colorectal cancer cell lines (HCT-116, RKO) with PIK3CA mutation were treated with 0, 2, 4, 8 mM/L aspirin." (PMID 32000660, 2020). "On the other hand, PIK3CA protein expression was correlated with PIK3CA gene amplification in lung and colorectal cancer." (PMID 33287350, 2020). "In particular, aspirin has been reported to be effective against PIK3CA-mutated colorectal cancer (CRC); however, little information is available on how the PIK3CA gene status affects its efficacy." (PMID 32365457, 2020). "HTC116 cells are microsatellite unstable (MSI phenotype), CIN-negative (like 10–20% of colorectal cancers), CIMP-positive, and harbor mutations in the KRAS and PIK3CA genes." (PMID 32916986, 2020). "PIK3CA protein expression was correlated with PIK3CA gene amplification in the lung and colorectal cancer." (PMID 33287350, 2020). "Mutations in PIK3CA will lead to overexpression of phosphorylated PI3K, promoting growth and proliferation of colorectal cancer cells." (PMID 32000660, 2020). "The M1043V mutation of PIK3CA is known to activate the PI3K p110α kinase subunit and has been detected in colorectal cancer patients." (PMID 31769426, 2019). "We first examined the mutation status of the KRAS, PIK3CA and BRAF genes in human colorectal cancer cell lines." (PMID 31769426, 2019). "A recent study demonstrates that MLN0128 can overcome resistance to everolimus and reduce tumor size by 20% in PIK3CA-mutant colorectal cancers." (PMID 31277692, 2019). "Primary colorectal cancers frequently harbor somatic mutation of KRAS (~40%), BRAF (~10–15%) and PIK3CA (~10–20%)." (PMID 31769426, 2019). "According to statistical analysis of the COSMIC database, colorectal carcinoma cells contain high rates of the gene mutation of KRAS (34%), PIK3CA (14%) and BRAF (10%), the major downstream signaling molecules of EGFR." (PMID 31367332, 2019).
colorectal cancer (continued). "In colorectal cancer (CRC), mutations of EGFR downstream targets occur especially in the GTPase KRAS in up to 45% and in the phosphatidylinositol-4,5-bisphosphate 3-kinase, catalytic subunit alpha (PIK3CA) in up to 30% of patients." (PMID 30001368, 2018). "The aim of FOCUS4-D was to test the efficacy of AZD8931 in patients with colorectal cancer whose tumours are wild-type for BRAF, PIK3CA, KRAS, and NRAS mutations." (PMID 29254887, 2018). "Recent evidence showed how combined analysis of KRAS and PIK3CA mutations, MET and PTEN expression in primary tumors and corresponding metastases in colorectal cancer demonstrated discordance between the two sites." (PMID 30282914, 2018). "PIK3CA is a component of the PI3K signalling pathway and is frequently mutated at hotspots in either exon 9 or 20 in colorectal cancer." (PMID 30598662, 2018). "To test for the generality of the MRS-detected data, we also treated PIK3CA mutant HT29 colorectal carcinoma cells with MK-2206 at 5xGI50 (GI50 = 0.4 μM) for 24 h." (PMID 30377337, 2018). "In summary, our findings provide valuable in vitro data to further support the use of aspirin in patients with PIK3CA-mutant colorectal cancer." (PMID 29152088, 2017). "The relationship between somatic or germline genetic variants and the chemopreventive use of aspirin is not limited to patients with PIK3CA-mutant colorectal cancer." (PMID 29152088, 2017). "The frequencies of PIK3CA mutations were 17.5%, 36.4%, and 16.7% in HNSCC, breast, and colorectal cancer, respectively." (PMID 28108737, 2017). "BKM120, a direct PIK3CA inhibitor, and BEZ234, a dual PIK3CA and mTOR inhibitor, exert pro-apoptotic effects on gastric and colorectal cancer cell lines." (PMID 29207615, 2017). "Multiple studies have demonstrated that proportions of colorectal cancers with specific molecular features such as MSI, high-level CIMP, and BRAF and PIK3CA mutations gradually increase along the bowel subsites from rectum to ascending colon." (PMID 27391152, 2016). "Patients with obesity and patients with colorectal cancer of poor differentiation, lymph node metastasis, advanced TNM stage, MSI, KRAS, BRAF or PIK3CA mutations had shorter overall survival." (PMID 26515606, 2016). "In the colorectal cancer set, KRAS (42.5%), PIK3CA (17.8%) and KIT (10.9%) were the most frequently mutated genes." (PMID 26968814, 2016). "In the present study, we found a microRNA binding site polymorphism rs141178472 in the PIK3CA 3′-UTR is associated with the expression and risk of colorectal cancer." (PMID 25834816, 2015). "We aimed to investigate the association between a miR-520a binding site polymorphism rs141178472 in the PIK3CA 3′-UTR and the risk of colorectal cancer (CRC) in a Chinese Han population." (PMID 25834816, 2015). "PIK3CA gene that encoded the catalytic p110-alpha subunit of PI3K has been described to be commonly mutated in various cancers, including colorectal cancer." (PMID 25834816, 2015).
colorectal cancer (continued). "In the present study, we observed an association between PIK3CA 3′-UTR polymorphism rs141178472 and risk of colorectal cancer." (PMID 25834816, 2015). "The four genes linked to colorectal cancer (NRAS, PIK3CA, MCC, APC) all show lower methylation in the AA/YRI groups." (PMID 25742137, 2015). "The panel allows the detection of mutations that are currently considered as actionable (NRAS, KRAS) or putatively actionable (BRAF, PIK3CA) in colorectal cancer." (PMID 26047774, 2015). "Increased synergistic activity of the drug combination was identified in colorectal cancer cell lines with concomitant KRAS and PIK3CA mutations." (PMID 26136684, 2015). "In one Phase I study, colorectal cancer patients underwent prospective molecular profiling for mutations in KRAS, BRAF, PIK3CA and expression levels of PTEN and pMET." (PMID 25401499, 2014). "In colorectal cancer (CRC), the PIK3CA gene, encoding the p110α catalytic subunit of class I PI3Ks, has been found to be mutated in 10–20% of CRC tumor specimens." (PMID 25401499, 2014). "Similar to the results with K-Ras inhibitor, mutations in PIK3CA and reduction in PTEN promote resistance of B-Raf V600E colorectal cancer cells to vemurafenib." (PMID 24276379, 2013). "Collectively, our data suggest that PF-04691502 exhibits potent anticancer activity in colorectal cancer by targeting both PIK3CA (H1047R) mutant CSCs and their derivatives." (PMID 23826249, 2013). "To model PIK3CA-activating mutations in the late stages of human cancer, we used two types of cancer cells derived from the highly metastatic SW48 colorectal cancer cell line." (PMID 23986086, 2013). "Recent interest arose for PIK3CA as a potential predictive marker of personalized therapy for colorectal carcinoma and a target for specific pharmaceutical agents." (PMID 23785428, 2013). "In our colorectal cancer (CRC) explant model, we also found that a PIK3CA mutation was associated with increased sensitivity to saracatinib and that Src inhibition resulted in a decrease in the activation of the Src and Akt pathways." (PMID 23342270, 2012). "Model VARI-LTM-041 colorectal cancer contained three mutations (KRAS and two PIK3CA mutations) that were also present in the matching tumor." (PMID 22709571, 2012). "In summary, we observed a moderate rate of KRAS mutations (145/478; 30.3%) or PIK3CA mutations (67/384; 17.4%) and a very low rate of BRAF mutations (1/384; 0.3%) in a cohort of primary colorectal carcinomas." (PMID 22931052, 2012). "In colorectal cancer (CRC), PIK3CA activating mutations have been described at frequencies of 10-20%, with two distinct regions, the helical and kinase domains, harbouring up to 80% of mutations." (PMID 21473780, 2011). "Clinicopathological and lifestyle characteristics of colorectal cancer cases by stratified PTEN expression and PIK3CA mutation status." (PMID 21473780, 2011). "In order to understand the importance of KRAS, PIK3CA and BRAF mutations for the progression of the various types of colorectal cancer, we compared the frequency of these oncogenic events in the series of polyps and in 50 MSI and 53 MSS CRC." (PMID 18782444, 2008). "Nothing is known on the relationship between PIK3CA mutations and CIMP or MLH1 methylation in colorectal carcinomas." (PMID 18782444, 2008). "MSI and MSS colorectal carcinomas harbour PIK3CA in 8 of the 50 (16%) and in 6 of the 53 (11.3%) cases, respectively." (PMID 18782444, 2008).